YES1P1 (YES1 pseudogene 1)
Synonyms: D22S670; formerly SYR; YES2; YESP
Gene: Processed pseudogene on chromosome 22 (25,647,261 to 25,649,232, forward strand). Ensembl gene ENSG00000224003.
Diseases named in the same sentence as YES1P1 in open-access papers:
YES1P1 is named in the same sentence as 1 disease in open-access papers, as found by Europe PMC text mining. Sharing a sentence is not in itself a finding about the gene and the disease.
YES1P1 shares sentences with these, for which no sentence is quoted: tumour (1 paper).